RELA (RELA proto-oncogene, NF-kB subunit)
Diseases named in the same sentence as RELA in open-access papers (continued):
Sharing a sentence is not in itself a finding about the gene and the disease.
pancreatitis (4 papers, 2012 to 2023). Inflammation of the pancreas. "In an experimental pancreatitis model in mice, the acinar cell specific knockout of RelA, coding for the p65 subunit of NFκB, significantly increased disease severity." (PMID 37881430, 2023). "Given the importance of the NFκB pathway in the pathophysiology of pancreatitis, mRNA levels for the key transcription factor RelA and the inhibitory protein IκBα were measured." (PMID 35336721, 2022). "Previous researches showed that the active RelA/p65 NF-κB subunit played an essential role in systemic inflammatory response in pancreatitis." (PMID 22529518, 2012). "A number of murine pancreatitis models, centered around the use of cerulein, suggest that NF-κB activation in the pancreas is damaging, due to constitutive acinar cell canonical NF-κB activation targeting IKK2 (IKKβ) or nuclear translocation of p65/RelA." (PMID 34572737, 2021).
Stroke (4 papers, 2012 to 2025). Sudden impairment of blood flow to a part of the brain due to occlusion or rupture of an artery to the brain. "Flowchart illustrating the protective effect of zinc on stroke through various stages: GWAS analysis and NHANEs database, bioinformatic analysis, diagnostic model, pathway analysis showing autophagy, and genes involved (RELA, TNFSF10, NFE2L2, FADD, DDIT3, CFLAR)." (PMID 40969765, 2025). "We therefore propose that RELA hyperactivation during stroke disrupts autophagic flux, sustaining proinflammatory cytokine release and driving infiltration and activation of monocytes and CD56^dim NK cells." (PMID 40969765, 2025). "Building on this mechanistic insight, potential therapeutic compounds targeting RELA emerged as candidates for stroke treatment." (PMID 40969765, 2025). "RELA emerged as a central hub in our zinc–stroke network and is notably the central subunit of the NF-κB transcription factor complex." (PMID 40969765, 2025). "After stroke, we observed translocation of RelA from the cytoplasm to the nucleus in neurons within the peri-infarct area." (PMID 37204689, 2023). "The relationship between NF-κB and stroke was studied by detecting the expression of RelA and p50 in brain tissue in six patients after death." (PMID 33953677, 2021). "Our study provides new evidence that inhibition of 1B/(−)IRE DMT1 expression, per se or through RelA-Lys310 hypo-acetylation, might be a potential therapeutic approach to counteract post-ischemic neurodegeneration in stroke patients." (PMID 22666436, 2012). "The key genes encompass critical pathways such as autophagy (e.g. NFE2L2, DDIT3, NAMPT), apoptosis (e.g. CFLAR, FADD) and NF-κB signaling (e.g. RELA, TNFSF10), suggesting a multifactorial involvement of these pathways in stroke pathophysiology." (PMID 40969765, 2025).
Behçet syndrome (3 papers, 2023 to 2026). "Almost half of these patients had been previously diagnosed with more common rheumatologic entities (such as Behcet’s Disease; BD) prior to the discovery of their pathogenic RELA variants." (PMID 36926348, 2023). "In Behçet syndrome, rare variants in TNFAIP3, RELA, and NFKB1 genes have been identified, underscoring the importance of NF‐κB overactivation." (PMID 39964335, 2025).
chronic kidney disease (3 papers, 2015 to 2023). Impairment of the renal function secondary to chronic kidney damage persisting for three or more months. "Herein, we found the coordinated overexpression of genes encoding RelA/p65 (a subunit of NF–κB) and HNF1α in the livers of chronic renal failure (CRF) rats—an experimental model of CKD." (PMID 36012158, 2022). "The SNP rs11820062 in RELA also showed a significant association with chronic kidney disease susceptibility (OR = 1.088, p = 8.0 x 10−5)." (PMID 26678048, 2015). "We found two independent DNA variants in the NFκB transcription factor genes RELA and NFKB1 (rs11820062 and rs12509403, respectively) that associate with kidney function and chronic kidney disease susceptibility in the human population." (PMID 26678048, 2015). "We used data from a large genome-wide association study to examine whether common SNPs in any of the genes encoding the kidney aging transcription factors (STAT1, STAT3 and the canonical NFκB complex genes RELA and NFKB1) show an association with kidney function or chronic kidney disease." (PMID 26678048, 2015).
chronic pancreatitis (3 papers, 2007 to 2023). A chronic inflammatory process causing damage and fibrosis of the pancreatic parenchyma. "Using chronic pancreatitis mouse models, they showed that the NF−κB RelA/p65 expressions in acinar cells were associated with protective effects against inflammation." (PMID 37092523, 2023). "Ductular proliferates in chronic pancreatitis showed an elevated cytoplasmic expression of RelA when compared to unaffected parenchyma, with four out of six cases scoring as cytoplasmic positive for RelA." (PMID 17622249, 2007).
colon adenocarcinoma (3 papers, 2024). "Further, they found that TNF-α can promote NFE2L3 transcription in colon adenocarcinoma through activating transcription factor p65 (RELA) which can bind to the first intron of NFE2L3." (PMID 39149514, 2024).
diffuse large B-cell lymphoma (3 papers, 2016 to 2025). "Furthermore, the nuclear overexpression of RELA was found to be significantly associated with a poor prognosis in patients with diffuse large B-cell lymphoma." (PMID 33194633, 2020). "In Diffuse Large B-cell Lymphoma (DLBCL), elevated anti-apoptotic BCL2-family proteins (e.g., MCL1, BCL2, BCLXL) and NF-κB subunits (RelA, RelB, cRel) confer poor prognosis." (PMID 40819126, 2025).
endothelial dysfunction (3 papers, 2021 to 2022). In vascular diseases, endothelial dysfunction is a systemic pathological state of the endothelium (the inner lining of blood vessels) and can be broadly defined as an imbalance between vasodilating and vasoconstricting substances produced by (or acting on) the endothelium. "Different stimuli related to endothelial dysfunction, such as vascular stress, oxysterols, and inflammation, have been reported to upregulate Eng gene transcription via transcription factors Kruppel Like Factor 6 (KLF6), liver X receptor alpha (NR1H3) and NF-κB p65 (RELA)." (PMID 36160139, 2022).
fatty liver disease (3 papers, 2011 to 2025). A reversible condition wherein large vacuoles of triglyceride fat accumulate in liver cells via the process of steatosis. "RelA-mediated NF-κB signaling activation promotes immune cell recruitment and activation, exacerbating hepatic steatosis." (PMID 39910053, 2025). "Two loci, NFKBIB and RELA, are involved in NFKB signaling pathway; PNPLA3 is known for its association with fatty liver disease; and SH3B2 has been associated with a multitude of traits and disease including myocardial infarction." (PMID 21533024, 2011). "However, depletion of RelA significantly increased liver weight (P < 0.01), liver TG content (P < 0.01), serum ALT (P < 0.01), and TC levels (P < 0.05), thus exacerbating the effects of HFD-induced hepatic steatosis, and apoptosis (P < 0.01)." (PMID 39910053, 2025). "To understand the role of hepatocyte RelA expression in MASLD in vivo, we induced hepatic steatosis in mice with or without RelA depletion." (PMID 39910053, 2025).
gastric adenocarcinoma (3 papers, 2007 to 2024). "In gastric adenocarcinoma, the prognostic impact of RelA expression appears to be somewhat conflictive, as overexpression was reported both to be an indicator of adverse and favourable patient prognosis." (PMID 17622249, 2007). "Positive immunoreactivity was observed in 51 (51 %) and 58 (58 %) gastric adenocarcinomas for NFKB1 and RELA staining respectively." (PMID 26801246, 2016).
gout (3 papers, 2020 to 2025). A condition characterized by painful swelling of the joints, which is caused by deposition of urate crystals. "The results showed that key transcription factors such as CEBPB, STAT3, RELA, and NFKB1 may be involved in the pathogenesis of gout by directly regulating the transcriptional levels of these genes." (PMID 40606658, 2025). "RELA and NFKB1 are the core components of the classic NF-κB signaling pathway, directly involved in the regulation of various pro-inflammatory genes (such as CXCL8 and PTGS2), driving gout-related inflammatory responses." (PMID 40606658, 2025). "The core targets of plantain for treating gout are MAPK1, RELA, TNF, NFKBIA, and IFNG, and the key pathways are pathways in cancer, hypoxia-inducible factor-1 (HIF-1) signaling pathway, interleukin (IL)-17 signaling pathway, Chagas disease (American trypanosomiasis), and relaxin signaling pathway." (PMID 33149752, 2020).
hepatitis B (3 papers, 2020 to 2022). "Most targets were associated with cancer, the PI3K-AKT signaling pathway and hepatitis B. The targets with the largest number of participating pathways were AKT1, RELA, and MAPK1, which participate in 21, 19, and 19 pathways, respectively." (PMID 36591458, 2022). "The core targets of plantain for hyperuricemia are RELA, MAPK1, NFKBIA, CASP3, CASP8, and TNF, and the main pathways are pathways in cancer, apoptosis, hepatitis B, IL-17 signaling pathway, and toxoplasmosis." (PMID 33149752, 2020). "There are 31 intersection targets for hyperuricemia, the main targets are RELA, MAPK1, NFKBIA, CASP3, CASP8, and TNF, and the main pathways include pathways in cancer, apoptosis, hepatitis B, IL-17 signaling pathway, and toxoplasmosis." (PMID 33149752, 2020).
Hodgkins lymphoma (3 papers, 2015 to 2017). A heterogeneous group of malignant lymphoid neoplasms of B-cell origin characterized histologically by the presence of Hodgkin and Reed-Sternberg (HRS) cells in the vast majority of cases. "Malignant diseases, such as the Hodgkin lymphoma express high levels of RelA in both Hodgkin and Reed-Sternberg cells." (PMID 25893721, 2015). "In 1999, Krappmann and colleagues described a constitutive NF-κB-activity with NF-κB-complexes containing RELA and c-REL in malignant cells derived from Hodgkin’s disease." (PMID 28767691, 2017).
ischemic stroke (3 papers, 2013 to 2025). A stroke disorder caused by obstruction of blood flow to the brain, due to thrombotic (local blood clot formation) or embolic (due to a blood clot or other material traveling from another site) event. "RelA is a major subunit of the pro-inflammatory transcription factor NF-κB protein complex that plays a significant role in neuronal death following acute insults to CNS like ischemic stroke." (PMID 24265774, 2013). "Thus, the RelA subunit of the activated p50/RelA dimer plays a key role in the onset of neurodegenerative processes induced by ischemic strokes, as well as glutamate or beta-amyloid toxicity, while another c-Rel subunit in activated NF-κB dimers determines the resistance of neurons to brain strokes." (PMID 40650173, 2025).
liver diseases (3 papers, 2025). "RelA, also known as nuclear factor kappa B p65, plays a crucial role in the pathogenesis of various liver diseases." (PMID 39910053, 2025). "RelA signaling performs various roles in liver diseases, with diverse functions across different liver cell types." (PMID 39910053, 2025).
liver inflammation (3 papers, 2014 to 2025). "In this study, we uncover a novel mechanism in which SIRT7-mediated deacetylation of RELA at K119 promotes liver inflammation and fibrosis." (PMID 41322258, 2025). "Our study provides novel insights into how the acetylation at different lysine sites influences RELA functions, which may have new implications on effective strategies for fighting against liver inflammation and fibrosis." (PMID 41322258, 2025). "The acetylation of RELA declined remarkably in the BSL and HHO groups, with aggravated liver inflammation and fibrosis compared to the control." (PMID 41322258, 2025).
lupus (3 papers, 2023 to 2026). "Among them, we identified pathogenic or likely pathogenic variants in genes previously associated with monogenic lupus, including a novel C1QA variant as well as other lupus-associated genes (COPA, ADAR, TLR7, IKZF3, RELA, PTPN11, SERPING1)." (PMID 41930824, 2026). "STAT1 and RELA (p65) are hub differential TFs between LN and normal kidneys, and the differential TFs in lupus renal tissues were mainly enriched in T-cell-related signaling." (PMID 36829595, 2023).
myeloid leukemia (3 papers, 2014 to 2019). A clonal proliferation of myeloid cells and their precursors in the bone marrow, peripheral blood, and spleen. "A previous study demonstrated that RELA could form a complex with SP1 and bind to the promoter region of KIT in myeloid leukemia cells." (PMID 31363162, 2019).
myocardial infarction (3 papers, 2011 to 2022). Gross necrosis of the myocardium, as a result of interruption of the blood supply to the area, as in coronary thrombosis. "SOD1 overexpression, RELA blockade, and diminished MyD88-mediated inflammation can enhance functional and metabolic recovery and greatly decreased myocardial infarction, while ADIPOR2 is required for revascularization." (PMID 32565767, 2020). "Activated RELA/p65 results in myocardial infarction, and activation of EGFR-dependent pathway strengthens cardiac fibrosis and exacerbates cardiac dysfunction in myocardial infarction." (PMID 36248430, 2022).
prostate tumors (3 papers, 2015 to 2024). "Gene expression of FZD5, DVL3, RELA, MAPK9, CTNNB1, and SNAI1 is higher in metastatic prostate tumors as compared to primary prostate tumors." (PMID 27191743, 2016). "The proof-of-principle experiments using CpG-siRNAs to target tumorigenic NF-κB/RELA and STAT3 signaling in xenotransplanted TLR9+ prostate tumors confirmed therapeutic efficacy of such strategy." (PMID 26046794, 2015). "Compared to the primary prostate tumors, mRNA level of NFKBIA, DUSP6, PLCB3, and SMAD4 are lower in metastatic prostate tumors, while mRNA level of RELA and SNAI1 exhibit opposite trend." (PMID 27191743, 2016).
small cell lung carcinoma (3 papers, 2011 to 2023). Small cell lung cancer (SCLC) is a highly aggressive malignant neoplasm, accounting for 10-15% of lung cancer cases, characterized byrapid growth, and early metastasis. "In addition, depletion of RELA-mediated nuclear signaling has been reported to delay tumor growth in small cell lung cancer." (PMID 37963919, 2023).
steatosis (3 papers, 2016 to 2025). Increased lipid within the cytoplasm of cells. "We utilized an in vitro steatosis model with or without RelA knockout in HepG2 cells or RelA silencing in LO2 cells to validate our findings." (PMID 39910053, 2025). "Dual-luciferase reporter assays confirmed the transcriptional activation between RelA and HNF1α, highlighting the lack of reciprocal transcriptional activation between these factors in hepatocyte steatosis." (PMID 39910053, 2025). "RelA depletion only resulted in mild hepatocyte steatosis, with less than 5% of degenerative hepatocytes and no detectable inflammatory cell infiltration, fibrotic tissue proliferation, or hepatic apoptosis (P > 0.05)." (PMID 39910053, 2025). "Global analysis of the activities of 500 transcription factors using promoter motif inference (see Experimental Section) showed that activities of RELA and IRF1, known mediators of steatosis, liver inflammation, and injury, were significantly increased in MASH." (PMID 39605182, 2025).
ulcerative colitis (3 papers, 2020 to 2024). An inflammatory bowel disease involving the mucosal surface of the large intestine and rectum. "Together, these results demonstrated that Rab27A plays a crucial role in ulcerative colitis progression through regulating the miR‐124‐3p/STAT3/RelA pathway." (PMID 32815642, 2020). "Furthermore, we clarified that Rab27A stimulated the STAT3/RelA signalling pathway by binding with miR‐124‐3p to promote the progression of ulcerative colitis." (PMID 32815642, 2020). "Mechanistically, Rab27A could regulate the miR‐124‐3p/STAT3/RelA axis to promote apoptosis and ROS production in ulcerative colitis." (PMID 32815642, 2020). "In addition to the insights into the pathology of this disease, we found a new pathway in the mechanism of UC: Rab27A, by regulating miR‐124‐3p, can activate the STAT3/RelA signalling pathway, which may provide novel therapeutic approaches with great impact in ulcerative colitis." (PMID 32815642, 2020).
vitiligo (3 papers, 2023 to 2024). Generalized well circumscribed patches of leukoderma that are generally distributed over symmetric body locations and is due to autoimmune destruction of melanocytes. "Based on the results of network pharmacology, molecular docking was performed to validate the binding modes of the top three active components (i.e., luteolin, quercetin, wogonin) and the top three FHB-vitiligo targets (i.e., RELA, STAT3, AKT1)." (PMID 37575231, 2023). "Consistent with the bioinformatic analysis results, GABARAPL2 and USP8 mRNA levels were raised in vitiligo lesions, whereas the mRNA levels of RELA, TBC1D17, and SP1 were decreased." (PMID 37287971, 2023). "Then, five mitophagy hub genes (GABARAPL2, SP1, USP8, RELA, and TBC1D17) were identified using two machine learning algorithms, and these genes showed high diagnostic specificity for vitiligo." (PMID 37287971, 2023). "Furthermore, GABARAPL2, RELA, TBC1D17, and USP8, except of SP1, are implicated in cellular responses to stress and external stimuli; External stimuli, such as stress and oxidative stress, are vital factors in the etiology of vitiligo." (PMID 37287971, 2023). "Through LASSO regression analysis and the random forest algorithm, we screened five mitophagy-related hub DEGs (GABARAPL2, USP8, RELA, SP1, and TBC1D17) in vitiligo." (PMID 37287971, 2023). "The results showed elevated GABARAPL2 and USP8 and decreased RELA, SP1, and TBC1D17 in vitiligo compared to healthy controls, which were consistent with bioinformatic analysis results." (PMID 37287971, 2023). "In addition, network pharmacology analysis identified AKT1, RELA, and STAT3 as key targets of FHB for vitiligo treatment." (PMID 37575231, 2023).
acute kidney injury (2 papers, 2014 to 2026). Sudden and sustained deterioration of the kidney function characterized by decreased glomerular filtration rate, increased serum creatinine or oliguria. "However, the role of RelA - a key component of the canonical NF-κB heterodimer - in regulating lymphatic growth and kidney function following acute kidney injury (AKI) remains unexplored." (PMID 41575998, 2026).
astrocytomas (2 papers, 2011 to 2020). "The expression of constitutively activated RelA/NF-κB is associated with malignancy in astrocytomas and plays a critical role in tumor invasion." (PMID 21479220, 2011).
celiac disease (2 papers, 2019). An autoimmune genetic disorder with an unknown pattern of inheritance that primarily affects the digestive tract. "In our analysis we focused on NFKBIA gene, as well as on RELA and TNFAIP3 genes that, similarly to NFKBIA, have been associated with susceptibility to celiac disease." (PMID 31049595, 2019).
chronic mucocutaneous ulceration (2 papers, 2022). "Heterozygous loss-of-function (LoF) mutations causing RelA haploinsufficiency have been reported as a cause of chronic mucocutaneous ulceration and familial Behçet’s disease." (PMID 36250618, 2022).
Cirrhosis (2 papers, 2022 to 2023). A chronic disorder of the liver in which liver tissue becomes scarred and is partially replaced by regenerative nodules and fibrotic tissue resulting in loss of liver function. "Botanical drugs and gut microbiota target MAPK1, VEGFA, STAT3, AKT1, RELA, JUN, and ESR1 in the treatment of hepatitis B cirrhosis, and their combined use has shown promise for cirrhosis treatment." (PMID 38029250, 2023).
colorectal adenocarcinoma (2 papers, 2021 to 2024). The most common type of colorectal carcinoma. "A significant difference in the expression of NF-κB was found when the immunohistochemical labeling of RelA protein, the p65 component of NF-κB, was applied to normal colorectal mucosa (9.3%), colorectal adenoma (54.0%), and colorectal adenocarcinoma (71.9%)." (PMID 39031216, 2024).